AOC3 (amine oxidase copper containing 3)
Description:
Catalyzes the oxidative deamination of primary amines to the corresponding aldehydes with the concomitant production of hydrogen peroxide and ammonia. Has a preference for the primary monoamines methylamine and benzylamine. Could also act on 2-phenylethylamine but much less efficiently. At endothelial cells surface can also function as a cell adhesion protein that participates in lymphocyte extravasation and recirculation by mediating the binding of lymphocytes to peripheral lymph node vascular endothelial cells in an L-selectin-independent fashion. [Isoform 2]: Has no semicarbazide-sensitive amine oxidase (SSAO) activity.
Synonyms: SSAO; VAP-1; VAP1; HPAO
Tractability: Small molecule: a structure with a bound ligand is known; a high-quality ligand is known; it has a high-quality binding pocket; it belongs to a druggable protein family. Antibody: a drug acting on it is in phase 2 or 3 trials; UniProt places it where antibodies can reach, with high confidence; its Gene Ontology location is reachable by antibodies, with high confidence; UniProt predicts a signal peptide or a membrane-spanning region. PROTAC: a small molecule that binds it is known.
Target class: Enzyme; Oxidoreductase
Chemical probes: CHEMBL2392121, CHEMBL3110303
Gene: Protein-coding gene on chromosome 17 (42,851,184 to 42,858,130, forward strand). Ensembl gene ENSG00000131471.
Subcellular location: Cell membrane
Subcellular location (Human Protein Atlas): Cytosol; Golgi apparatus
Pathways (Reactome):
Metabolism: Phase I - Functionalization of compounds
Gene Ontology:
Molecular function: calcium ion binding; copper ion binding; identical protein binding; primary methylamine oxidase activity; protein binding; protein heterodimerization activity; quinone binding
Biological process: amine metabolic process; cell adhesion; inflammatory response
Cellular component: cell surface; cytoplasm; early endosome; endoplasmic reticulum; Golgi apparatus; membrane; microvillus; plasma membrane
Genetic constraint (gnomAD): Loss-of-function variants: 51 observed, 60.96 expected, observed/expected ratio (o/e) 0.84, 90% interval 0.67 to 1.06. The upper end of that interval is the gene's LOEUF score, 1.06, which puts it in group 4 of 6, group 1 being the genes least tolerant of losing a copy. Missense variants: 850 observed, 988.69 expected, observed/expected ratio (o/e) 0.86, 90% interval 0.81 to 0.91. Synonymous variants: 384 observed, 408.69 expected, observed/expected ratio (o/e) 0.94, 90% interval 0.86 to 1.02.
Homologues: Orthologues: chimpanzee AOC3 (99% identical), dog AOC3 (89% identical), rabbit AOC3 (84% identical), mouse Aoc3 (83% identical), guinea pig AOC3 (74% identical), zebrafish aoc2 (41% identical). Paralogues in human: AOC2 (65% identical), AOC1 (38% identical).
Diseases named in the same sentence as AOC3 in open-access papers:
AOC3 is named in the same sentence as 155 diseases in open-access papers, as found by Europe PMC text mining. Sharing a sentence is not in itself a finding about the gene and the disease. The quoted sentences say what the papers report.
diabetes (24 papers, 2012 to 2025). "In healthy humans, serum levels of soluble AOC3 are low, while increased levels have been observed in the sera of patients suffering from diabetes, heart failure, and liver diseases." (PMID 36983904, 2023). "The high activity level of AOC3 has been reported to participate in the development of type 2 diabetes mellitus, Alzheimer's disease, atherosclerosis and stroke." (PMID 35527426, 2022). "Circulating activity of AOC3/SSAO increase during biological stress in multiple pathologic states including HF, obesity, atherosclerosis, diabetes and inflammatory liver diseases, and are an independent marker of mortality in patients with chronic HF44–48." (PMID 36418363, 2022).
atherosclerosis (22 papers, 2013 to 2025). A disease characterized by the build-up of fatty material and calcium deposition in the arterial wall resulting in partial or complete occlusion of the arterial lumen. "Adding the causal genes ACE, AGT, AGTR1, and REN to list 2+ (n = 9+4) revealed AOC3 with at least one causal gene to be associated with Transition Metal Ion Binding (GO:0046914, q = 2.288x10-2), and Atherosclerosis (q = 2.821x10-5)." (PMID 39480826, 2024). "AOC3 was associated with Proteins Involved in Age-Related Macular Degeneration (q = 9.982x10-4) and Proteins involved in Atherosclerosis (q = 1.975x10-2)." (PMID 39480826, 2024). "Of note, the level of soluble AOC3 is associated with risk factors for atherosclerosis, carotid artery intimal thickening and clinical cardiovascular events in asymptomatic individuals, which is consistent with our scRNA‐seq results." (PMID 35527426, 2022). "Serum AOC3, described as an independent marker of carotid atherosclerosis in diabetic patients and associated with cardiovascular risk factors and early atherosclerotic manifestations, was found to increase in mouse serum in the late stage of atherosclerosis." (PMID 36176983, 2022). "It was found that the level of AOC3 was positively correlated with copper content, serum AOC3 concentration could predict the risk of atherosclerosis, and AOC3 expression level in arterial tissue was also positively correlated with the severity of atherosclerosis." (PMID 37928399, 2023). "Secreted in the serum by VSMC, AOC3 is an independent marker of atherosclerosis and can extend to coronary artery disease." (PMID 36176983, 2022). "Exploration of cell-type expression of AOC3 during the development and progression of murine and human atherosclerosis was performed by co-immunofluorescent staining between AOC3 and α-SMA, CD31, and MOMA-2." (PMID 36176983, 2022). "Inhibition of AOC3 in limiting atherosclerosis is controversial, showing sometimes either a reduction, an increase in atheromatous plaques, or a stabilization through a phenotypic switch of VSMC." (PMID 36176983, 2022). "AOC3 seems an interesting potential target in the treatment of atherosclerosis." (PMID 36176983, 2022). "The differences in protocol settings using AOC3 inhibitors could explain the discrepancies regarding AOC3 effects on atherosclerosis." (PMID 36176983, 2022). "However, it is difficult to conclude that whether AOC3 plays a protective or destructive role in the entire development of atherosclerosis." (PMID 35527426, 2022). "This problem will most likely not exist when atherosclerosis is therapeutically targeted with specific AOC3 inhibitors." (PMID 36176983, 2022). "Furthermore, we also found that the expression of AOC3 in stable plaques and non‐IPH plaques is significantly up‐regulated by integrating the original data from different patients with atherosclerosis." (PMID 35527426, 2022). "Moreover, we have demonstrated LOX as a regulator of SSAO activity, VAP-1 protein and Aoc3 mRNA expression in early passage rat aortic VSMCs, highlighting SSAO as an important novel therapeutic target for the treatment/prevention of atherosclerosis." (PMID 36902376, 2023). "This suggests that AOC3 may have an important role in atherosclerosis independent of its canonical inflammatory effect." (PMID 36176983, 2022).
Obesity (14 papers, 2012 to 2026). Accumulation of substantial excess body fat. "In closing, we also comment on a possible link of the adipocyte-associated AOC3 to the clinical symptoms of obesity, noting that there are several routes that could increase AOC3 activity, leading to an accompanying inflamed state." (PMID 22238597, 2012). "Inhibitors of AOC3 were also shown to have anti-obesity effects." (PMID 32315567, 2020). "BMI-predictive proteins included established obesity markers and obesity-related proteins, including adiponectin, CRP, IGFBP1, IGFBP2, PRG4, SHBG, apolipoproteins (APOA4, APOF) and inflammatory response proteins (A2M, APCS, LBP, HSPG2, HP, AOC3, ITGB1, VNN1)." (PMID 39972214, 2025).
breast carcinoma (9 papers, 2016 to 2023). "In breast cancer, positive expression of AOC3 was associated with higher pathological grade and Ki-67 expression." (PMID 37257820, 2023). "In breast cancer, AOC3 is highly expressed and is positively associated with lymphatic invasion and distant metastasis." (PMID 36189307, 2022). "In HER-2-negative breast cancer, AOC3 negativity was associated with short DFS and OS (p = 0.026 and p = 0.037, respectively), and in the breast cancer showing lymph node metastasis, AOC3 negativity was associated with short DFS and OS (p = 0.038 and p = 0.012, respectively)." (PMID 29261141, 2017). "Therefore, high expression of AOC3 can be associated with high expression of the gene involved in cancer cell migration in HER-2-positive breast cancer stroma." (PMID 29261141, 2017). "Studies analyzing breast cancer tissue and benign tissue with proteomic analysis showed that AOC3 expression was decreased in breast cancer, suggesting the possibility that the stage-specific marker, AOC3, may affect the prognosis of breast cancer." (PMID 29261141, 2017). "Stromal AOC3 expression was high in luminal B and HER-2-type breast cancer, and MAO-A expression was high in luminal A and luminal B. Expression of amine oxidase proteins, especially AOC3, is associated with prognosis in breast cancer subgroups." (PMID 29261141, 2017). "We observed that stromal AOC3 was highly expressed in luminal B and HER-2-type breast cancer, and MAO-A was highly expressed in luminal A and luminal B. To the best of our knowledge, ours is the first study to present the results of AOC3 expression in breast cancer." (PMID 29261141, 2017). "No previous study has examined the expression of AOC3 in breast cancer tissues, and the expression of AOC3 in breast cancer stroma has not yet been reported." (PMID 29261141, 2017). "In the absence of AOC3 expression in breast cancer, we can assume possibilities of a poor prognosis by low protective, local immune responses." (PMID 29261141, 2017).
colorectal cancer (9 papers, 2016 to 2025). A primary or metastatic malignant neoplasm that affects the colon or rectum. "AOC3 is an endothelial adhesion protein, the low-level AOC3 facilitated mesenchymal transformation and correlated with lymph node and hepatic metastasis in colorectal cancer." (PMID 38084139, 2023). "In colorectal cancer, AOC3 expression is reduced in both in situ tissues and serum, and reduced AOC3 expression is related to poorer prognoses." (PMID 36189307, 2022). "However, the expression of AOC3 is downregulated in some cancers such as aggressive prostate and colorectal cancers." (PMID 40496615, 2025). "The endothelial adhesion molecule, vascular adhesion protein-1 (VAP-1, AOC3) promotes lymphocyte recruitment to tumours, although the contribution that VAP-1 makes to lymphocyte recruitment in human colorectal cancer (CRC) is unknown." (PMID 26912327, 2016). "Notably, AOC3 was identified as an autophagy-related biomarker predictive of CDN4 subtype, which could be an important prognostic marker in colorectal cancer." (PMID 38461356, 2024).
chronic kidney disease (8 papers, 2016 to 2025). Impairment of the renal function secondary to chronic kidney damage persisting for three or more months. "AOC3 is abundant in the activated endothelium of vascularized tissues, including the retina, kidney, and liver, and is associated with vascular diseases and inflammatory conditions such as chronic kidney disease, chronic liver disease, and DM." (PMID 33845913, 2021). "Elevated levels of soluble AOC3 are found in type 1 and type 2 DM, correlating with complications such as end-stage renal disease, cardiovascular mortality, and DR." (PMID 33845913, 2021).
inflammatory liver disease (8 papers, 2012 to 2024). "From genomic analysis, we identified several markers perturbed in CLOCKΔ19 qHSCs as potential markers of disease and show Amine Oxidase Copper containing 3 (AOC3) progressively tracks liver disease severity in patient serum samples." (PMID 37371052, 2023). "AOC3 is one such gene which is upregulated in CLOCKΔ19 qHSCs and was previously shown to correlate to human liver disease." (PMID 37371052, 2023). "Genes altered in this primed CLOCKΔ19 qHSC state may provide biomarkers for early liver disease detection, and include AOC3, which correlated with disease severity in patient serum samples." (PMID 37371052, 2023).
Arthritis (7 papers, 2015 to 2024). Inflammation of a joint. "Nevertheless, some of these genes participate in nervous system development (CLSTN2, TUBB2B), inflammation including arthritis (AOC3) and stress-induced responses (C10orf10), making them promising molecular candidates in OA-driven pain." (PMID 29973527, 2018).
fibrosis (6 papers, 2017 to 2026). the formation of excess fibrous connective tissue in an organ or tissue in a reparative or reactive process. "In addition, the oxidase activity of AOC3 was positively correlated with the development of fibrosis in a bleomycin-induced pulmonary fibrosis mouse model." (PMID 40559419, 2025).
pulmonary fibrosis (5 papers, 2020 to 2025). Chronic progressive interstitial lung disorder characterized by the replacement of the lung tissue by connective tissue, leading to progressive dyspnea, respiratory failure, or right heart failure. "The role of AOC3 in pulmonary fibrosis development has been shown using AOC3-deficient mice, which were protected from lung fibrosis, as well as in wild-type mice treated with an AOC3 inhibitor." (PMID 32842664, 2020). "Amine oxidase copper-containing-3 (AOC3) is an enzyme with a role in the development of pulmonary fibrosis." (PMID 41597294, 2025). "As a new marker of myofibroblasts, AOC3 may play a role in pulmonary fibrosis and thus induce asthma." (PMID 33194371, 2020). "Amine oxidase copper-containing 3 (AOC3), previously identified as an IF/TA-related DEG, and carcinoembryonic antigen-related cell adhesion molecule 3 (CEACAM3) expression were reportedly upregulated in PBMCs from idiopathic pulmonary fibrosis patients." (PMID 37623492, 2023).
astrocytoma (4 papers, 2017 to 2023). "However, AOC3 overexpression is associated with poor prognosis of astrocytoma, which is different from the results in this study." (PMID 29261141, 2017).
gastric cancer (4 papers, 2016 to 2019). A primary or metastatic malignant neoplasm involving the stomach. "However, in previous studies on colon and gastric cancer, serum AOC3 level was higher in cancer patients than in healthy subjects, and a low preoperative level of serum AOC3 indicated poor prognosis." (PMID 29261141, 2017).
lung carcinoma (4 papers, 2022 to 2025). "Downregulation of amine oxidase copper containing 3 (AOC3) was reported to decrease immune cell recruitment and promote lung cancer progression." (PMID 36211344, 2022). "Finally, the screening models for lung cancer were constructed by combining candidate protein markers (AOC3, CAT, CLEC3B, SEPP1, HBB) with tumor markers (CEA, CYFRA21-1, NSE) using machine learning." (PMID 40496615, 2025). "Furthermore, the expression of AOC3 was increased in the plasma of individuals with lung cancer, which was consistent with the results in the plasma of mice." (PMID 40496615, 2025). "The AOC3 protein was also identified and has been recently described to play a role in the reduction of immune cell recruitment and impacting the promotion and progression of lung cancer." (PMID 36737789, 2023). "A total of 6 genes (LYVE1, CLEC3B, FGA, AOC3, HYDIN, and HBB) exhibited differential expressions in the plasma of LUSC and the area of the lesion in lung cancer (including LUAD and LUSC)." (PMID 40496615, 2025). "The C-type lectin domain family 3 member B (CLEC3B), membrane primary amine oxidase (AOC3), hemoglobin subunit beta (HBB), catalase (CAT), and selenoprotein P (SEPP1) were screened as candidate protein markers for early-stage lung cancer." (PMID 40496615, 2025). "The candidate protein markers were investigated based on the TCGA database, supplemented by Kaplan-Meier plotter and Oncomine analysis, and then AOC3, CLEC3B, CAT, SEPP1, and HBB were selected as potential candidates for early-stage lung cancer." (PMID 40496615, 2025). "There was a strong correlation between the survival time of individuals with lung cancer and 7 genes (CLEC3B, AOC3, HBB, CAT, SEPP1, FGA, and ORM1, P<0.05)." (PMID 40496615, 2025). "The candidate protein markers (AOC3, CAT, CLEC3B, SEPP1, HBB) and traditional tumor markers (CEA, CYFRA21-1, NSE) were combined to construct screening models for lung cancer by machine learning techniques." (PMID 40496615, 2025). "AOC3 is an endothelial adhesion protein, and low-level AOC3 facilitated mesenchymal transformation and decreased CD4+ T cell recruitment to lung cancer." (PMID 38084139, 2023). "The expressions of candidate protein markers were dynamically observed at the various phases of lung carcinogenesis, which revealed that AOC3, CAT, CLEC3B, SEPP1, and HBB may be the key molecular markers of early lung cancer lesions." (PMID 40496615, 2025).
Nephropathy (4 papers, 2016 to 2025). A nonspecific term referring to disease or damage of the kidneys. "Also, TLR4, AOC3, IRF4, and TNFAIP6 were not differentially expressed in non-drug-induced AKI models including IRI and UUO models, which was unexpected and additional evidence of the specificity of these hub genes in drug-induced kidney damage." (PMID 37063876, 2023).
age-related macular degeneration (3 papers, 2012 to 2024). Age-related loss of vision in the central portion of the retina (macula), secondary to retinal degeneration. "AOC3 (amine oxidase copper containing 3) was implicated by causal genes ELN and FBLN5 in age related macular degeneration which typically develops post-middle age, but it has previously been associated with Autosomal Dominant Cutis Laxa." (PMID 39480826, 2024).
acute kidney injury (2 papers, 2019 to 2024). Sudden and sustained deterioration of the kidney function characterized by decreased glomerular filtration rate, increased serum creatinine or oliguria. "AOC3 has previously been suggested as a biomarker in drug induced acute kidney injury." (PMID 39480826, 2024).
colon cancer (2 papers, 2022 to 2023). "AOC3, another downregulated gene in CAFs, is associated with the enrichment of pathways in colon cancer." (PMID 35991839, 2022).
endometriosis (2 papers, 2020). The growth of functional endometrial tissue in anatomic sites outside the uterine body. "The identification of AOC3 in the proteomic and transcriptomic experiments, along with the strong immunoreactivity found in lesions, prompted us to further investigate the role of the enzyme in an endometriosis inoculation model." (PMID 32001775, 2020). "Upregulation of the enzyme amine oxidase 3 (AOC3) may contribute to the oxidative stress within endometriosis as in vivo studies indicate that inhibition of AOC3 may provide analgesic effects in endometriosis." (PMID 33302392, 2020).